RAG1 (recombination activating 1)
Diseases named in the same sentence as RAG1 in open-access papers (continued):
Sharing a sentence is not in itself a finding about the gene and the disease.
infection (continued). "Similar decreases in Tnf and Il6 mRNA were observed in mice on the Rag1−/− background at 3 hr post-infection, confirming that these differences are due to a defect in innate immunity in the absence of HOIL-1." (PMID 25599590, 2015). "FACS purified Il4gfp+Ifnar–/–or Il4gfp+Ifnar+/+ Th2 cells were transferred to Rag1–/–recipient mice, subsequently infected with P. chabaudi and analyzed at day 8 post-infection." (PMID 26147567, 2015). "In order to determine the mRNA levels of the major T cell transcription factors (Foxp3, Tbet, GATA3 and RORγC) after reconstitution of Rag1-/- mice, RT-PCR analyses of total lung RNA were performed after 2 and 6 weeks of infection." (PMID 26512987, 2015). "Similar to Rag1-/- mice, both WT and PHIL mice showed transcriptional signatures associated with a general reprogramming of muscle following infection; however there were distinct differences between WT and PHIL." (PMID 26720604, 2015). "To assess the importance of functional, specific lymphocytes for the changes in the levels of the markers used in this study, we also carried out similar infection experiments in rag1 (−/−) mutants." (PMID 24968056, 2014). "The other 3 IL2rg/RAG1 KO rabbits died within 2 months (because of infection) when kept in cleaner conditions in isolation after weaning." (PMID 25408890, 2014). "The outcome of infection with M. tuberculosis of Rag1−/− mice reconstituted with control or Socs3fl/fl lck cre T cells was then compared." (PMID 23853585, 2013). "Recent studies have confirmed, further, that S. mansoni failed to receive appropriate signals from the host immune system after infection of immunodeficient mice (RAG-1-/-), which resulted in the appearance of attenuated forms." (PMID 22414188, 2012). "Although Rag1−/− mice succumbed to ROP5 deficient (RHΔku80Δrop5) infection, death was delayed compared to wild type (RHΔku80) infection." (PMID 23144612, 2012). "Consistent with the findings in the bead targeting experiments phagocytosis of M. bovis BCG was significantly reduced in rag1–/– macrophages compared to recombination-competent rag1+/+ control mice (n = 7) after 6 hours of infection." (PMID 22114556, 2011). "Infection of Rag1−/− mice led to the development of a generalized disease, with disseminated poxvirus lesions in the face, forepaw and tail, which culminate with the mortality of 100% of the animals." (PMID 21526210, 2011). "Again, as in Rag1−/− mice, clinical signs of disease in nu/nu animals correlate with a higher viral replication in the initial site of infection (t test, p<0.05) and in the spleen at days 10 and 15 p.i.." (PMID 21526210, 2011). "al. identified a role for Myd88, an adapter protein of TLR signaling, and RAG1, necessary for antibody production, in protection from infection and disease." (PMID 20386712, 2010). "By 42 days post-infection, all RAG1-/- mice had consistent, high levels of MNV in both duodenum/jejunum and distal ileum, as well as several other tissues (data not shown)." (PMID 19079577, 2008). "We have previously shown that MNV infected RAG1-/- mice have high levels of viral RNA present in multiple tissues up to 90 days post-infection." (PMID 19079577, 2008). "The importance of adaptive immunity in control of MNV infection is indicated by the observation that RAG1-/- mice develop persistent MNV infection while wild type (WT) mice can clear infection with some strains of MNV." (PMID 19079577, 2008). "In RAG1- and RAG1/γc-deficient mice, infection persisted under a normal diet but worm burdens were partially reduced on HFD, indicating that diet enhances parasite control through immune-independent, possibly microbiota-mediated pathways." (PMID 41630160, 2026). "This was also reflected by the finding that CD4+ T cell recruitment to the brains of Rag1–/– animals progressively decreased when adoptive transfer was delayed, with the most dramatic impairments observed at day 7 after infection, again aligning with the onset of biofilm development." (PMID 39989461, 2025).
infection (continued). "For microglia, ingenuity pathway analysis (IPA) revealed significant reductions in Type I and Type II IFN signaling, T cell activation/signaling, and immune activation pathways including IL-12 and IL-1 across the top 3 microglial clusters in Rag1–/– mice primarily at day 7 after infection." (PMID 39989461, 2025). "Similar findings were observed with leukocyte infiltrates, where monocyte, G-MDSC, and PMN recruitment to the brain was restored to WT levels when Rag1–/– mice received Th1 or Th17 cells at day 3 but were less effective when adoptive transfer was initiated at day 7 after infection." (PMID 39989461, 2025). "Rag1−/− PEP-null mice also have prolonged survival over Rag1−/− PEP-WT at 5e4 PFU infection." (PMID 40791464, 2025). "Although B cell infiltrates are minimal during craniotomy infection, they may partially contribute to the phenotypes observed in Rag1–/– mice that can be explored in future studies with muMT–/– animals." (PMID 39989461, 2025). "Single-cell RNA-Seq (scRNA-Seq) revealed transcriptional heterogeneity in brain CD3+ infiltrates, with CD4+ cells most prominent that displayed Th1- and Th17-like characteristics, and adoptive transfer of either subset in Rag1–/– animals during early infection prevented S. aureus outgrowth." (PMID 39989461, 2025). "Meanwhile, Ifng−/− and Rag1−/− mice have the same survival rate compared to WT mice, suggesting the induction of a completely maladaptive T cell response during lethal infection, which is a very different infectious course compared to humans." (PMID 40568097, 2025). "Comparison of the Mono/Mac1 cluster between WT and Rag1–/– animals at day 3 after infection identified only 50 significantly differentially expressed genes representing 0.027% transcriptional coverage, which translated to a lack of significantly enriched pathways at this time point." (PMID 39989461, 2025). "Similarly, SPF Rag1-/- mice became more vulnerable to CR infection following Cefoxitin administration, as evidenced by augmented body weight loss and mortality." (PMID 39630719, 2024). "Importantly, we observed early control of N. caninum in both WT and RAG1−/− mice, as indicated by a decline in N. caninum-derived luciferase signal on the second day of infection." (PMID 39445806, 2024). "In an M.tb model of infection, fewer M.tb colony‐forming units (CFUs) were observed in the lungs of Rag1‐KO mice that received mito‐transferred naïve CD4+ T cells (p = 0.004) or non‐manipulated naïve CD4+ T cells from old mice (p = 0.01), compared to control infected Rag1‐KO mice." (PMID 37990641, 2024). "To examine whether the lethal infection of CR occurs restrictedly in Il22-/- mice, we carried out oral CR infection in GF Rag1-/- mice, another immunocompromised strain where the V(D)J recombination activation gene Rag1 was deleted." (PMID 39630719, 2024). "Rag-1-/- mice showed successful “granuloma” formation in the lungs at two-weeks post-infection." (PMID 38198478, 2024). "Specifically, in Rag1−/− mice that lack adaptive immunity, an intraperitoneal (i.p.)injection of a PA solution 12 hours prior to intravenous (i.v.)infection with Candida albicans lead to a significant decrease in kidney fungal burden, compared to infected mice only pretreated with a Veh solution." (PMID 37197687, 2023). "Despite being heavily expanded in Rag1–/– at baseline, the relative contribution, if any, of Actinobacteriota in infection is presently unknown." (PMID 34445184, 2021). "In contrast to rag1-/-, CD4 genomically deficient mice (cd4-/-) showed similar densities of CD45+ cells and parasites spreading all over the ME and Arc as compared to those in WT mice early after infection." (PMID 34587172, 2021). "Indeed, Rag1−/− and Tcrbd−/− mice, which lack T cells, displayed a significantly higher fungal burden on day 7 and day 14 after infection with strain 101, compared to WT mice." (PMID 32719409, 2021).
infection (continued). "However, MA-CCHFV infection was lethal in young-female WT mice and female Ifnar1-/- and Rag1-/- mice demonstrating that resistance to MA-CCHFV by female mice is age-dependent and requires both innate and adaptive host responses." (PMID 33416494, 2021). "However, in Rag1-/-Tpl2-/- mice, which lacks mature B and T lymphocytes, the relative concentrations of circulating immune cells were increased during the infection with Staphylococcus xylosus, compared with Rag1-/- mice." (PMID 34735542, 2021). "Analysis of the Ly6chi population in the liver at 7 dpi after infection with Pru-tdTom showed that a proportion of infected and uninfected cells express iNOS in the Rag1−/−mice, but iNOS levels were markedly reduced in the Rag1−/−; Il1rl1−/− mice." (PMID 33929319, 2021). "We noted weaker slicing of the vsiRNA target by the pan-Ago IP from Stat1/2−/− mice than from Rag1−/− mice in response to NoVΔB2 infection (compare lanes 3 and 5), which appeared to correlate with the lower levels of vsiRNAs induced by NoVΔB2 in Stat1/2−/− mice than in Rag1−/− mice." (PMID 32753500, 2020). "Moreover, we observed no obvious differences in Ago2-mediated RNA slicing by the endogenous miRNA-RISC isolated from Rag1−/− or Stat1/2−/− mice after either mock or NoVΔB2 infection." (PMID 32753500, 2020). "Notably, the numbers of Ly6Chi monocytes, F4/80hi CD11blo macrophages, eosinophils and mature neutrophils in STAT1/RAG1 DKO mice were significantly greater than in STAT1 KO mice following infection." (PMID 32310998, 2020). "After 5 days of infection Rag1 KO mice lost significantly more body weight compared to WT mice." (PMID 33193324, 2020). "Hence, as IFN-I production and signaling is necessary for the development of the lethal disease in LCMV-infected STAT1 KO mice, it remained possible that the survival of STAT1/RAG1 DKO mice following infection was due to impaired IFN-I production." (PMID 32310998, 2020). "Such enhanced inflammatory response can result in more severe pathology as observed in the infection with R. typhi upon the adoptive transfer of immune CD4+ T cells into C57BL/6 RAG1-/- mice where CD4+ T cells, when transferred late in the infection, promote MΦ-mediated inflammation in the brain." (PMID 33091016, 2020). "Also, in Rag1−/− mice infected with Mtb, NK cells can mediate a certain degree of protection against the infection via the production of IFN-γ." (PMID 33117393, 2020). "On day 21 post-infection, compared with day 0, wild-type mice exhibited an increase in serum IgM, IgG, and lung IgM, and serum and lung IgM were each detectable in Rag1−/− mice that received B cells 14 and 21 d post-infection, albeit at much lower levels than in wild-type mice." (PMID 28837391, 2018). "However, brain CFUs of Rag1−/− mice were significantly higher than those of wild-type mice on days 14 and 34 post-infection, with median brain CFUs < 10-fold higher in Rag1−/− mice on day 14 and nearly 105 times higher on day 34 after infection (p < 0.05)." (PMID 28837391, 2018). "Gene set enrichment analysis of the data obtained in the SVCV infection and poly(I:C) injection experiments revealed important contributions of immune-related multigene families to the rapid defense mechanisms observed in rag1−/− fish." (PMID 28243233, 2017). "Indeed, we found that lymphocytes begin to arrive in the granuloma by 7 days after infection and that bacterial burdens diverge between rag1 heterozygotes and mutants by 28 days." (PMID 28934421, 2017). "Finally, we show that passive immunization of Rag1 knockout mice with Hirep1 antibodies completely prevented the establishment of infection in 48% of the mice, demonstrating an isolated role for neutralizing antibodies in controlling infection." (PMID 29312283, 2017). "Furthermore, CD8 T cell function is maintained during the persistent phase of infection and adaptive immune cells from persistently infected mice are functional when transferred to Rag1-/- recipients." (PMID 27327515, 2016).
infection (continued). "Moreover, adoptive transfer of immune CD4+ T cells still protects approximately 60% of C57BL/6 RAG1-/- mice when applied later in advanced infection when the bacteria start to rise." (PMID 27875529, 2016). "However, whereas C57BL/6 RAG1-/- mice are capable to control the infection for more than 80 days before R. typhi reappears in the central nervous system, infection of CB17 SCID mice with R. typhi leads to a complete different outcome." (PMID 27548618, 2016). "To do so, we utilized a similar adoptive transfer model and monitored bacterial loads in the lungs and spleens until 42 days post-infection (p.i.), after which unreconstituted RAG1 KO mice succumb and further comparisons with T cell reconstituted mice cannot be made." (PMID 27244558, 2016). "Furthermore, cytokine levels from vaginal washes of M28 GAS infected Rag1−/− and WT mice demonstrated that the Rag1−/− mice produced greater quantities of IL-1β, IL-6, and TNFα at 14, 21, and 28 days post-infection compared to WT mice." (PMID 27241677, 2016). "We recently showed these hyperplastic crypts appear less susceptible to infection by C. rodentium whereas the highly susceptible Rag1 deficient (-/-) mice (lacking T and B cells) are severely impaired in developing infection-induced IEC hyper-proliferation." (PMID 26285214, 2015). "Infection of mice lacking adaptive immunity (Rag1-/- mice) with a T6SS-deficient mutant results in a hypervirulent phenotype that is characterized by high numbers of intracellular bacteria in systemic organs." (PMID 26485303, 2015). "Quantification of RB50 and RB50ΔclpV in respiratory tract organs of Rag1-/- mice on day 21 (prior to death with RB50ΔclpV infection) revealed similar numbers of Bordetella indicating that the hypervirulence of the ΔclpV strain is not caused by increased bacterial load in the respiratory tract." (PMID 26485303, 2015). "In that work, mice given IL-12 showed a significant augment in IFN-γ production at the beginning of infection and reduction of Th1/Th2-related cytokines at the late stage of infection, similarly to what was observed in the present study for Rag1-/- mice injected with CD4+Foxp3- T cells." (PMID 26512987, 2015). "RAG1-/- mice again showed persistent infection as evidenced by prolonged viremia." (PMID 26115459, 2015). "Fungal growth and dissemination in Rag1-/- mice were evaluated after 2 and 6 weeks of infection." (PMID 26512987, 2015). "Viral loads in organs of RAG1-/- mice following footpad infection with 3 log10 PFU of wt CHIKVa." (PMID 26115459, 2015). "In Rag1-/- mice RB50ΔclpV proportions increased to 8% in the spleen and 4% in the liver on day 3 p.i., indicating that clpV and adaptive immune components both limit intracellular recovery from systemic organs early during infection." (PMID 26485303, 2015). "Viral loads in organs of RAG1-/- mice following SC infection with 3 log10 PFU of wild-type CHIKVa." (PMID 26115459, 2015). "Since the parasites seemed to exhibit a severe fitness defect that might lead to clearance of the infection by the mouse immune system, we switched to immunodeficient RAG-1 -/- mice for cloning purposes." (PMID 25032958, 2014). "As there is a general understanding that immune responses will result in selection of mutated variants we examined the immune status of the infected fry at time of infection (0.15 g size) by analyzing the mRNA expression of RAG-1, T cell receptor (TCR) and IgM (BCR) by real-time PCR." (PMID 23431359, 2013). "At 2 wpi, Nos2b expression was significantly lower in rag1 (−/−) fish (19.6-fold, SD = 30.3) compared to the wt fish (123-fold, SD = 16), suggesting that adaptive responses affect Nos2b induction during the early phase of infection preceding the latency." (PMID 23028333, 2012). "Indeed, the transfer of T cells prior to vaccination was fully sufficient to protect RAG-1−/− mice against lethal infection, whereas control RAG-1−/− mice all died despite MVA immunization (P = 0.0003)." (PMID 22396645, 2012).
infection (continued). "Thus TLR4- and TNF-α-dependent functions, such as efficient phagocytosis and killing, appear to be sufficient to prevent lethal infection by RB50ΔsigE in Rag1−/− mice." (PMID 22897969, 2012). "Moreover, beginning at the second week of infection, all the Rag1−/− mice clearly showed clinical signs of disseminated disease, such as ruffling fur, arched back and disseminated poxvirus lesions, primarily on the face, forepaw and tail." (PMID 21526210, 2011). "Finally, NUDE athymic mice showed a similar outcome of infection as Rag1−/−, and passive transfer of WT T cells to Rag1−/− animals proved fully effective in preventing morbidity/mortality." (PMID 21526210, 2011). "Rag1-/- mice died between day 10 and 12 after primary infection with influenza A virus, and injection of natural IgM antibodies could delay death for two more days." (PMID 20667098, 2010). "Compared to Rag1‐KO mice that received either PBS or non‐manipulated naïve CD4+ T cells from old mice, Rag1‐KO mice that received mito‐transferred naïve CD4+ T cells from old mice had a significant delay in IAV‐induced morbidity (weight loss) by day 8 post‐infection." (PMID 37990641, 2024). "Increased abundance of strict anaerobes (Clostridia and Bacteroidota) and of Proteobacteria was observed in Rag1–/– and NSG mice, respectively, with the former showing a microbiome configuration associated with resistance and the latter with susceptibility to the infection, as already reported." (PMID 34445184, 2021). "The high IL-5 levels seen in STAT1 KO and STAT1/RAG DKO mice may contribute to early weight loss and more severe thickening of the basement membrane of bronchial epithelial cells, which was exaggerated in STAT1/RAG1 DKO mice compared with STAT1 KO mice following infection." (PMID 32310998, 2020). "However, in our study, increased viral RNA levels in STAT1/RAG DKO mice compared with the RAG1 KO mice in the early days of infection suggests that in RAG1 KO mice, there is STAT1-dependent, likely IFN-I-dependent, robust, early restriction of viral replication." (PMID 32310998, 2020). "However, it seems unlikely that IL-5 has an instrumental role in the lethality of LCMV-infected STAT1 KO mice since STAT1/RAG1 DKO mice had greater IL-5 levels than STAT1 KO mice following infection, suggesting that adaptive immune cells inhibit the production of IL-5." (PMID 32310998, 2020). "However, regardless of what event(s) or cue(s) trigger the development of enhanced immunity to SVCV in rag1−/− zebra fish, this model, integrating rag1−/− zebra fish and subsequent infections reproduces, at least to some extent, the development of non-specific, protective immunity in vivo." (PMID 28243233, 2017). "Finally, adoptive transfer of CD8+ T cells from immune mice protects C3H/HeN mice against challenge with a normally lethal dose of R. conorii and C57BL/6 RAG1−/− mice against lethal infection with R. typhi, even when transferred into mice with already established infection." (PMID 28770333, 2017). "In either Rag1–/– recipient, adult CD4+T cells differentiated into Th1s similar to levels seen in primary infection." (PMID 40280180, 2025). "Th1 and Th17 transfer also reduced the frequency of G-MDSC and PMN infiltrates in the brain of Rag1–/– recipients compared with Rag1–/– mice alone, suggesting that CD4+ T cells regulate granulocyte recruitment during craniotomy infection." (PMID 39989461, 2025). "Particularly, the significant increase in the post-challenge clinical outcomes of ARPV/ZIKV-vaccinated Rag1 KO mice compared to vaccinated Tcra KO or muMt- KO mice may support the idea of a compensatory relationship between cellular- and humoral-mediated immunity during infection." (PMID 39388457, 2024). "At 3 weeks post infection, CD4 T cells from infected C57BL/6 mouse were transferred via the intravenous route to the RAG1 KO mice." (PMID 38977711, 2024).